LEP (leptin)
Diseases named in the same sentence as LEP in open-access papers (continued):
Sharing a sentence is not in itself a finding about the gene and the disease.
steatosis (continued). "However, the leptin levels have not been shown to correlate with the degree of steatosis or fibrosis, although some studies have previously reported patients with steatosis and NASH to demonstrate elevated levels of leptin." (PMID 22110476, 2012). "The upregulation of CD14 by leptin-mediated signaling in Kupffer cells is critical in regulating the hepatic inflammatory response to the bacteria-mediated progression of NASH, although even in a healthy liver may exist an activation of this via irrespective of the presence of steatosis." (PMID 33316927, 2020). "Indeed, when leptin was co-administrated in chow-fed mice also induced the upregulation of CD14 in Kupffer cells, which could lead to hepatic inflammation and fibrosis in the absence of steatosis." (PMID 33316927, 2020).
Anorexia (124 papers, 2004 to 2025). Lack of desire to eat (loss of appetite). "On the other hand, albumin level correlates inversely with leptin level, suggesting increased leptin secretion in a hypoalbuminemic state, causing anorexia." (PMID 40045433, 2025). "Reduced levels of leptin and elevated ghrelin can promote further weight loss and anorexia, which complicates nutritional management and disease progression." (PMID 41370490, 2025). "JAKi effectively treated cancer‐associated anorexia and adipose wasting in mice by targeting Interleukin 6 and leptin metabolism." (PMID 39564906, 2025). "STAT3 has been associated with AN and the transmission of leptin signaling in previous studies using the activity-based anorexia (ABA) rat model." (PMID 38849516, 2024). "Knocking down HSP90 in HEK293 Ob-Rb cell line attenuates leptin-induced STAT3 signaling associated with anorexia." (PMID 38336777, 2024). "The role of leptin and adiponectin in the regulation of food intake has been shown: an increased concentration of leptin causes anorexia and reflects the mass of adipose tissue." (PMID 37111210, 2023). "On the other end of the spectrum, elevated plasma leptin levels have been known to cause eating disorders leading to underweight and anorexia." (PMID 35886710, 2022). "Circulating leptin enters the brain through the blood–brain barrier and causes anorexia by neuronal inhibition in the hypothalamus." (PMID 35745267, 2022). "A comprehensive review of anorexia in spaceflight suggests that microgravity during spaceflight leads to increases in the two hormones (Leptin and GLP-1) that cause satiety." (PMID 35011072, 2021). "An adiposity excess causes insensitivity to leptin, deep anorexia, and a dysregulation of the innate and adaptive immune response, with an increase in susceptibility to respiratory infections." (PMID 32630032, 2020). "Histamine signaling being downstream of the anorexigenic hormones leptin and amylin suggests a mechanism of action in cancer-associated anorexia." (PMID 31921666, 2019). "Several studies have demonstrated that increased leptin concentration is associated with anorexia and muscle mass loss." (PMID 27307101, 2016). "Intra-day variation in leptin suggests that leptin level is associated with anorexia and eating behavior in patients with cancer cachexia, as well as amount of body fat." (PMID 25411961, 2014). "For instance, leptin is a significant modulator of the anorexia associated with infection, and treatment with leptin anti-serum can reverse LPS-induced anorexia." (PMID 23964195, 2013). "This is also supported by the fact that MIC-1 infusion can induce anorexia and weight loss in leptin-deficient mice." (PMID 22518191, 2012). "This manuscript will review the evidence and potential mechanisms mediating changes in the leptin pathway in the setting of anorexia and cachexia associated with chronic diseases." (PMID 22518191, 2012). "TB associated reductions of leptin are mediated independently by weight loss and prolonged inflammation, while leptin cannot account for the weight loss and anorexia associated with the disease." (PMID 21040518, 2010). "In cancer patients, leptin correlates with adiposity indices and, unlike in healthy individuals, is positively associated with appetite; however, low leptin levels in cachectic patients are likely a consequence of reduced fat mass, partially caused by anorexia." (PMID 41373779, 2025). "Studies have found that malnutrition is associated with anorexia and inadequate intake, tumor depletion, leptin, tumor-induced metabolic abnormalities in the body, and catabolic factors produced by the tumor in the circulation and cytokines produced by the host immune system." (PMID 37533569, 2023). "However, leptin suppresses FAA when administered continuously to leptin-deficient mice or to rats in an activity-based anorexia model." (PMID 37624889, 2023).
Anorexia (continued). "Eating disorders were found to be linked with oxytocin through leptin in the case of anorexia or through changes in oxytocin receptor genes, as seen in cases of bulimia and anorexia, promoting the idea that oxytocin could be used in treatment." (PMID 35888641, 2022). "Thus, the underlying mechanism by which amylin/leptin synergistically mediate anorexia and body weight loss remains to be determined." (PMID 35050175, 2022). "Leptin antagonism attenuated leptin-induced weight loss, loss of fat content, and anorexia." (PMID 34440723, 2021). "The higher levels of leptin might cause more pronounced and prolonged anorexia after open surgery compared with laparoscopic surgery." (PMID 34827598, 2021). "Although estrogen is known to inhibit food intake and seems to increase the serum leptin concentration, its deficiency in anorexia may also exaggerate anxiety." (PMID 32867089, 2020). "Similarly, STC2 treatment also induced anorexia in hyperphagic leptin-deficient mice, leading to a significant reduction in body weight and improvement of blood glucose levels." (PMID 29207625, 2017). "Thus, leptin deficiency attenuates LPS-induced anorexia, and further analysis has shown that both the PI3K and STAT3 signaling pathways in leptin receptor-expressing cells are required for the acute hypophagic response to LPS." (PMID 29213271, 2017). "In addition, increased serum levels of the satiety-signaling hormone leptin and the resultant anorexia response are generally associated with altitude sojourn or hypoxic training." (PMID 28386234, 2017). "Leptin was investigated as a possible causative agent for the anorexia in both species." (PMID 26017156, 2015). "Despite the correlation between body mass index and plasma leptin is usually preserved in IBDs, the mechanistic role of hyperleptinaemia in the onset of anorexia and weight loss associated with IBDs remains unclear." (PMID 21829567, 2011). "Thus, the acute decrease in leptin following LPS in our study may be associated with LPS-induced anorexia, as fasting is known to markedly inhibit leptin expression." (PMID 40583106, 2025). "Furthermore, LPS-induced fever and loss of appetite were found to be mediated by leptin through induction of IL-1β in the brain, a finding later confirmed by others, all evidence supporting leptin as a mediator of anorexia and cachexia in inflammatory diseases." (PMID 28154473, 2017). "Swimming or 6 weeks of voluntary roller exercise can improve hypothalamic leptin signaling and induce anorexia behaviors." (PMID 39590824, 2024). "Male VSG offspring exhibited a dysregulated response to exogenous leptin, failing to respond with canonical anorexia after a single dose." (PMID 37626574, 2023). "Together, these findings indicate that GALR2 is involved in SPX’s effects on leptin-induced anorexia." (PMID 35204737, 2022). "In this study, we report that GALR2 is involved in SPX’s effects on leptin-induced anorexia and POMC expression." (PMID 35204737, 2022). "As for the pathogenesis mechanism of anorexia, changes in 5-HT, inflammatory cytokines, WBCs, ghrelin, and leptin were analyzed in the studies." (PMID 35215322, 2022). "Our results revealed that SPX induces anorexia and leptin increases SPX expression via STAT3 signaling in the mouse hypothalamus, suggesting a possible role for SPX in the mediation of leptin’s anorexigenic effects in the hypothalamus." (PMID 35204737, 2022). "At a very early stage, LIF can increase leptin, leading to anorexia and weight loss, but due to adaptive changes in the body, the effects of LIF are disturbed, leptin expression is suppressed, and anorexic behavior is ameliorated." (PMID 35740622, 2022). "The low level of promoting anorexia hormone leptin and higher hunger hormone ghrelin levels has been found during short sleep in some experimental research." (PMID 34867820, 2021).
Anorexia (continued). "The aim of the present study was to determine the role of serum leptin in postoperative anorexia after laparoscopic gastric cancer surgery." (PMID 34827598, 2021). "Among other inflammatory cytokines, leptin, an adipokine, has been identified as a potential factor in the development of anorexia." (PMID 34827598, 2021). "This, along with anorexia and energy deprivation, leads to reduced leptin transcription in adipose tissue and low plasma leptin levels." (PMID 33809200, 2021). "We have, therefore, proposed that laparoscopic surgery produces lesser postoperative anorexia compared to open surgery by means of lowering the postoperative serum leptin levels." (PMID 34827598, 2021). "In our study, on the other hand, we were interested in the postoperative serum leptin dynamics and their relation to postoperative anorexia." (PMID 34827598, 2021). "Another cytokine shown to be of importance in the role of developing cachexia–anorexia is leptin, which is released from adipocytes and signals to the hypothalamus to regulate nutritional intake as a satiety cue." (PMID 33329046, 2020). "This is key when you consider reports that a low level of leptin was diagnosed in oncological patients, in which additional disturbances were found such as anorexia." (PMID 32531934, 2020). "Leptin has been shown to endorse central 5-HT turnover through nitric oxide (NO) dependent pathway, and it has been demonstrated that central leptin-induced anorexia is in part mediated by 5-HT2c receptor." (PMID 32033608, 2020). "TNF-α, IL-6 and IL-1 mimic leptin signaling and suppress orexigenic ghrelin and neuropeptide (NPY) signaling, which result in weight loss and anorexia." (PMID 32906727, 2020). "The co-administration of leptin and SHU9119 (a synthetic antagonist of both MCR3 and MCR4 receptors), attenuated leptin-induced anorexia and completely inhibited leptin-induced BAT increase in UCP1 mRNA levels." (PMID 32069871, 2020). "The role of hypothalamic astrocyte LepR signaling in energy homeostasis is well established in previous studies: knockdown of LepR in the hypothalamus leads to alterations in neural circuitry and attenuates leptin-induced anorexia in mice." (PMID 32152264, 2020). "The physiological role of histamine as an integral part of orexin signaling points to its possible role in the sleep disturbances of cancer patients and links it to leptin signaling, and thus anorexia and the circadian rhythmicity of NST in cancer cachexia." (PMID 31921666, 2019). "Administration of leptin can also reverse hypogonadism in women with hypothalamic amenorrhea, suggesting a potential role for leptin in the treatment of anorexia." (PMID 31220230, 2019). "Deletion of ObR in astrocytes diminishes leptin-induced anorexia and enhances fasting- or ghrelin-induced hyperphagia." (PMID 31447640, 2019). "Numerous studies have indicated that 5-HT2C receptor mediates leptin-induced anorexia, but reports regarding serotonin-leptin interactions are discrepant." (PMID 32116676, 2019). "In contrast, deletion of Trpc5 in all POMC neurons leads to an age-dependent increase in body weight, with increased food intake, decreased energy expenditure, and attenuated leptin-mediated anorexia, although glucose homeostasis was unchanged." (PMID 30304668, 2018). "Secretion of the “satiety hormone” leptin in response to LPS also contributes to inflammation-induced anorexia." (PMID 29213271, 2017). "Impaired ObR signaling in astrocytes leads to an altered glial morphology, increases the number of synapses onto POMC, and NPY/AgRP neurons and blunts leptin-induced anorexia." (PMID 28270795, 2017). "It is plausible that the male group experienced a rapid decline in leptin at 3 months primarily as a result of the reduced caloric intake and acute anorexia of the dietary proportion of the intervention." (PMID 28050279, 2016).
Anorexia (continued). "High circulating levels of leptin are expected to play an important role in the postprandial pathway of signals in anorexia of aging." (PMID 26828516, 2016). "It was previously reported that total level of AgRP is higher in obese subjects, although in another study it has been demonstrated that AgRP levels were lower in normal weight group compared with women with anorexia, probably due to increased leptin levels." (PMID 25034457, 2015). "This study has shown that immobilization stress-induced anorexia and decrease in body weight can be reversed by leptin injection." (PMID 24624061, 2014). "Leptin act in the hypothalamus, where leptin inhibits neuropeptide Y (NPY) neurons and causes anorexia." (PMID 23579596, 2013). "In the hypothalamus, leptin inhibits food intake through mTOR activation, and mTOR inhibition with rapamycin prevents leptin-induced anorexia." (PMID 22701480, 2012). "Injecting nesfatin-1 was shown to activate the PVN and result in leptin-independent melanocortin-mediated anorexia." (PMID 22518191, 2012). "Leptin, a regulator of eating behavior, has been shown to be a major determinant of anorexia in uremic animals via signaling through the hypothalamic melanocortin system." (PMID 21676262, 2011). "This balance is lost during cachexia, as even in front of a markedly reduced concentration of leptin in the plasma in tumour-bearing animals, anorexia is still present." (PMID 21861927, 2011). "Taken together, these findings suggest that baseline nutritional status may contribute to the prolonged increase in leptin concentration observed in the anorexia group." (PMID 40045433, 2025). "In addition, it has been reported that inflammation-induced anorexia is due to elevated levels of circulating leptin." (PMID 39691381, 2024). "Interestingly, leptin has been shown to produce not only anorexia, but also an alteration in core body temperature that resembles a sickness response." (PMID 38821928, 2024). "However, the decreased levels of leptin during fasting, which can be observed in eating disorders such as anorexia, also lead to infertility, due to reduced levels of LH and GnRH and inhibition at the stage of the primary follicle." (PMID 39797110, 2024). "Gastric cancer itself leads to malnutrition due to anorexia, which can occur due to mechanical obstruction by the tumor or even a state of cachexia, which involves the exaggerated release of pro-inflammatory cytokines and leptin dysregulation." (PMID 38747883, 2024). "They postulated that a relative increase in food intake in the setting of IDPN may be the result of relief of anorexia due to the suppression of increases in leptin that would otherwise be occurring." (PMID 39666754, 2024). "In the tumour-carrying state, malnutrition factors, such as cytokines, can mimic the excessive transmission of negative feedback signals from leptin, thereby inducing anorexia and weight loss, and ultimately malnutrition." (PMID 37533569, 2023). "Leptin can induce anorexia and regulates energy requirements, fat reserves, and food intake." (PMID 37452264, 2023). "Interestingly, in patients with anorexia, leptin and insulin enter the brain, inhibit the activity of NPY/AgRP neurons, simultaneously stimulate the activity of POMC/CART neurons, and inhibit food intake." (PMID 37452264, 2023). "It was shown that LIF could promote the expression of leptin at an early stage and generate anorexia." (PMID 35740622, 2022). "Although its role in chemotherapy-induced anorexia remains unclear, it is seen as an indicator of the severity of the disorder, as serum leptin levels have been reported to be low in anorexia-induced humans and rodents." (PMID 35215322, 2022). "A number of recent studies have shown that most CKD patients have inappropriately high leptin levels, and it has been speculated that leptin may be one of the factors mediating anorexia and wasting in this patient group." (PMID 36296981, 2022).